EGFR (epidermal growth factor receptor)
Diseases named in the same sentence as EGFR in open-access papers (continued):
Sharing a sentence is not in itself a finding about the gene and the disease.
rectal cancer (continued). "A higher percentage of patients with rectal cancer was in the EGFR inhibitor (22.7%) or no targeted therapies (24.6%) groups than in the VEGF inhibitor group (17.6%)." (PMID 36656585, 2023). "However, additional studies are still needed to clarify the role of EGFR and the predictive potential of the MAPK/AKT and PI3K/AKT/mTOR pathways in rectal cancer." (PMID 34321074, 2021). "The negative prognostic impact of middle/low rectal cancer in patients treated with first-line anti-EGFR was found to be independent in multivariate analyses of PFS and OS." (PMID 34188197, 2021). "Subgroup analyses for all patients and the limited population of patients with middle/low rectal cancer indicate that patients without metastasectomy showed higher OS in the non-first-line anti-EGFR treatment group than in the first-line group." (PMID 34188197, 2021). "The purpose of this study is to explore the relationship between ADC values obtained by RESOLVE and the main pathological prognostic factors of rectal cancer and to assess whether such ADC values correlate with the positive expression of EGFR." (PMID 30001205, 2018). "It seems that AKT1, EGFR, and TP3 are suitable drug targets to prevent rectum cancer progression." (PMID 30774817, 2018). "MUTKRAS is a negative predictor of benefit to anti-EGFR antibodies in colo-rectal cancer, while it seems to be a negative predictor of response to EGFR-TKIs in EGFR wild type (WTEGFR) NSCLC patients." (PMID 26799287, 2017). "On the other hand, in patients with locally advanced rectal cancer treated with preoperative chemoradiotherapy, EGFR gene copy number was neither predictive nor prognostic." (PMID 25216514, 2014). "In a subgroup analysis of rectal cancer, we found significantly better survival rates (p = 0.001) in patients with EGFR positivity (data not shown)." (PMID 24204699, 2013). "Finally, we applied our normalization strategy to the quantification of EGFR, HER2 and HER3 in 104 rectal cancer biopsies." (PMID 19368728, 2009). "Finally, we applied this strategy for the quantification of EGFR, HER2 and HER3 in rectal cancer biopsies." (PMID 19368728, 2009). "In this study, negative VEGF and positive EGFR expression were predictive of complete pathologic response to preoperative radiotherapy in patients with advanced rectal cancer." (PMID 18182986, 2008). "However, there was a trend toward shorter OS in middle/low rectal cancer patients who received anti-EGFR treatment as the first line than in those who received non-first-line EGFR treatment (27.8 months vs 33.6 months, P = 0.124)." (PMID 34188197, 2021). "Finally, there is currently no indication that anti-EGFR monoclonal antibodies, namely, cetuximab, should play a role in the perioperative treatment of all patients with locally advanced rectal cancer, not even of patients with (K)RAS WT tumors." (PMID 25861256, 2015). "Interestingly, KRAS mutation, known to be an adverse predictive and prognostic marker in mCRC patients treated with EGFR inhibitors, is less frequent in rectal cancer and does not convey the same predictive information." (PMID 22970381, 2012). "Therefore, appearing of EGFR and its ligand EGF as crucial elements of rectum cancer is not a surprising finding." (PMID 30774817, 2018).
brain cancer (66 papers, 2007 to 2026). A primary or metastatic malignant neoplasm affecting the brain. "The epidermal growth factor receptor (EGFR) has been implicated in a number of epithelial cancers (breast, lung and brain cancers) and has a role in cell growth, survival and migration." (PMID 34575943, 2021). "In brain cancer, one of the most widely investigated EGFR alterations is the EGFR transcript variant III (EGFRvIII), caused by varying DNA deletions in the gene that all affect mRNA splicing to exclude exons 2–7." (PMID 32650387, 2020). "Brain cancers also harbor higher levels of EGFR gene amplification and mutations that eventually lead to increased level of both wild-type (EGFRwt) and mutant EGFR." (PMID 28346397, 2017). "Aberrant expression/activation of EGFR is found in multiple human cancers, including medulloblastoma, the most prevalent pediatric brain cancer, and often has been associated with metastasis, poor prognosis, and resistance to chemotherapy." (PMID 25052069, 2014). "Thus, this technique can be useful for the better diagnosis of brain cancer associated with alteration of epidermal growth factor receptor (EGFR)." (PMID 40432717, 2025). "Importantly, IAPs expression in the ERK-MAPKi resistance group including 3 types of brain cancers were associated with sensitivity to EGFR inhibitor, PI3K/MTOR inhibitor and WNT signaling inhibitors." (PMID 31964418, 2020). "The aberrant activation of those EGFR signaling pathways, due to factors like cell-surface overexpression, autocrine activation, and mutations in the EGFR gene, is observed in various cancers, including lung, head and neck, cervical, colorectal, and brain cancers." (PMID 39126121, 2024). "As expected, scatter plot analysis of EGFR and GCLC co-expression showed that the distribution of EGFR tissue expression in normal brain samples (N = 3198) shifts toward higher expression levels in brain cancer tissue (N = 2750)." (PMID 39001381, 2024). "E-liquid exposure induced an increased level of EGFR phosphorylation in a dose-dependent manner in brain cancer cells and further induced the increased expression of ERK phosphorylation, a downstream effector of the EGFR signaling pathway." (PMID 35563421, 2022). "Ultimately, (iii) trispecific mAbs that can work against TfR, EGFR, and cytosol molecules that are essential to brain cancer cells can be produced using LassoGraft Technology®." (PMID 35884906, 2022). "EGFR is also a well-known driver of tumorigenesis in case of several types of cancers such as lung, breast and brain cancer." (PMID 34200663, 2021). "Panitumumab-IRDye800 is a fully humanized EGFR antibody currently undergoing early phase clinical trials for fluorescence-guided surgery of brain cancers (NCT03510208 and NCT04085887 for adult and pediatric HGGs, respectively)." (PMID 34158840, 2021). "We found that the suppression of c-Myc and EGFR/EGFRvIII significantly prolonged the survival of mice with orthotopic brain cancer." (PMID 34835657, 2021). "Through an in vitro study, we revealed the significance of the effect of e-liquid on brain cancer by confirming a direct relationship between e-liquid treatment and EGFR signal activation." (PMID 34495991, 2021). "The data suggested that e-liquid activates specific transducers of EGFR signaling, which influence the growth of brain cancer stem cells via the activation of the ERK pathway." (PMID 34495991, 2021). "In this study, we employ various genetic and pharmacology approaches to elucidate that TF is elevated in EGFR-mut lung and brain cancers in an mTOR-dependent manner." (PMID 32923403, 2020). "EGFR signaling is involved in cell growth and is frequently upregulated in various cancers such as lung, colon, and brain cancers." (PMID 30735525, 2019). "The THL delivery of DNA-based RNAi therapy was evaluated in a model of brain cancer that over-expressed the EGFR." (PMID 31998120, 2019).
brain cancer (continued). "The most common mutant form of EGFR in brain cancer is EGFRvIII which exhibits more oncogenic potential than EGFRwt." (PMID 28346397, 2017). "In brain cancer models, mostly two distinct mechanisms initiate NF-κB signaling: one is EGFR signaling and another, the deletion of the NFKBIA gene that encodes IκBα." (PMID 28346397, 2017). "The technology has also been used to investigate the PI3K pathway activities of brain cancer cells expressing mutant epidermal growth factor receptor (EGFR) after drug intervention targeting EGFR signaling." (PMID 27581736, 2016). "In conclusion, we developed a novel and promising strategy by using intracranial injection of EGFR-CAR-modified human NK cells followed by oHSV-1 administration to target human EGFR positive brain cancers such as BCBMs." (PMID 27050072, 2016). "Further, previous work from our laboratory has successfully labeled activated EGFR populations in live brain cancer cells by binding Qdots to the extracellular domain of EGFR and then inducing receptor activation to detect intracellular, activated EGFR." (PMID 22339792, 2012). "In this paper, we presented a novel multi-scale agent-based model to describe tumor growth with angiogenesis and study the response of brain cancer to EGFR tyrosine kinase inhibitors (TKIs)." (PMID 22935054, 2012). "The EGF receptor (EGFR) is over-expressed in primary brain cancer." (PMID 35745855, 2022). "The PMLA as a nanoplatform allows one to covalently attach a number of anticancer moieties, e.g., antisense oligonucleotides (AONs) targeting c-Myc or EGFR/EGFRvIII, and checkpoint inhibitor antibodies such as anti-PD-1 (αPD-1), to produce a multifunctional nanomedicine against brain cancer." (PMID 34835657, 2021). "We found that co-resistance between gefitinib and AMDs (i.e., gefitinib ↔ paclitaxel or gefitinib ↔ epothilone B) can serve as a proxy to represent co-resistance between all EGFR-TKIs and AMDs, at least based on the similar co-resistance frequencies in lung, breast, and brain cancers." (PMID 33850249, 2021). "In addition, we showed that the increased level of EGFR phosphorylation in brain cancer cells is due to e-liquid exposure." (PMID 34495991, 2021). "Collectively, our results suggest that mechanical compression applied on brain cancer cells could activate MEK1/Erk1 pathway through EGFR/Ras/Raf activation, which as it is widely known, is just upstream of MEK1." (PMID 31612114, 2019). "Binding of EGFR on brain cancer cells was visualized at a cellular level using confocal microscopy." (PMID 27050167, 2016). "In our study we chose gefitinib as the EGFR TKI to treat brain cancer." (PMID 22935054, 2012). "Recent studies showed that EGFR pathway plays an important role in the evolution of brain cancer." (PMID 22935054, 2012). "Crosstalk between EGFR and Met has been reported in breast, lung, and brain cancers." (PMID 22788954, 2012). "Abnormal activation of the epidermal-growth-factor receptor (EGFR) is due to either its overexpression or mutation, which mediates downstream-signaling overactivation and becomes an important driver of the malignant development of human cancers, including lung, head-and-neck, and brain cancers." (PMID 37240137, 2023). "Interestingly, 45–57% of GBM cases tested, showed activating mutations in the EGFR gene, which is one of the main activators of Ras/Raf/MEK1/Erk1/2 signaling axis and it is found to be involved in proliferation, migration and invasion of brain cancer cells." (PMID 31612114, 2019). "Furthermore, this strategy may also be feasible for other EGFR overexpressing tumors, including lung and brain cancers." (PMID 21912620, 2011).
brain cancer (continued). "For boron drug discovery using polymeric DDS targeting cell surface markers, there are reports of immunoliposomes containing an anti-EGFR antibody bound to the liposome surface and boron drug BSH for malignant brain tumors with high EGFR expression levels." (PMID 41361823, 2025). "To gain new insights into the impact of disease on co-expression of EGFR and GCLC genes, we analyzed the correlation between EGFR and GCLC co-expression in human normal brain and brain cancer tissues." (PMID 39001381, 2024). "The cell lines used in this study included breast, lung, prostate, ovarian, head and neck, and brain cancer cells along with the NIH3T3 panel of wild type, EGFR, and Her2 transfected cell lines." (PMID 34502481, 2021). "EGFR mediated activation of PKC is known to regulate cell matrix adhesion in breast and brain cancers." (PMID 32719793, 2020). "FBLN3 binds EGFR through its EGF like repeats inhibiting its activation and function in lung and brain cancer cells." (PMID 32719793, 2020). "Simultaneous occurrence of EGFR and phosphatase and tensin homolog (PTEN) alterations as well as an interplay between these two factors can be observed in various cancers such as cancers of the brain, lung and prostate." (PMID 30134822, 2018). "At relapse we evaluated the expression of tumor target proteins focusing on the protein expression profile often involved in brain cancers with possible therapeutic implications, such as PDGFR and EGFR." (PMID 24559248, 2014). "In human brain cancer, exogenous EGF significantly enhances the formation of neurosphere cultures, while inhibition of EGFR tyrosine kinase activity potently inhibits sphere formation." (PMID 23620784, 2013). "The epidermal growth factor receptor (EGFR) signaling pathway and angiogenesis in brain cancer act as an engine for tumor initiation, expansion and response to therapy." (PMID 22935054, 2012). "Activation of EGFR signaling upregulates VEGF and activates angiogenesis in human brain cancer cells." (PMID 17609662, 2007). "It was further demonstrated that two tTG inhibitors, the irreversible peptidomimetic Z-Don and the alternate substrate MDC, decreased EGFR expression, and increased EGFR ubiquitination, when applied to U87 MG or LN229 brain cancer cells, and that knockdown of tTG had similar effects." (PMID 30662957, 2018). "Where possible, EGFR expression was also confirmed in post-mortem tumor biopsy samples from the remaining brain cancer dogs (data not shown)." (PMID 27050167, 2016). "EGFR and GCLC displayed a significant positive correlation in normal brain tissue (Pearson R = 0.317, padj = 1.8 × 10−4), which strikingly decreased to a near-zero value in brain cancer (Pearson R = 0.0098, padj = 4.5 × 10−4)." (PMID 39001381, 2024).
pneumonitis (66 papers, 2012 to 2025). An inflammatory process affecting the lung parenchyma. "Although the incidence of fatal pneumonitis associated with third-generation EGFR-TKIs has historically been regarded as low, real-world data on osimertinib indicate an overall fatal pneumonitis rate of approximately 1.1%." (PMID 41585870, 2025). "The combination of programmed cell death protein 1 (PD-1) inhibitors with EGFR-TKIs, for example, has been associated with severe immune related adverse events (irAEs) such as pneumonitis." (PMID 40700234, 2025). "Pre-existing IP is considered one of the risk factors for drug-induced pneumonitis caused by molecular-targeted therapy, especially by EGFR-TKIs, along with factors such as older age, smoking history, and poor performance status." (PMID 38611005, 2024). "On the other hand, it turned out that concurrent use of EGFR-targeted therapy and immunotherapy in advanced EGFR-mutated NSCLC renders an unacceptably high risk of pneumonitis." (PMID 38756650, 2024). "The administration of EGFR-TKIs combined DCs loaded with 6Gy*3f-TEXs exhibited the potential to inhibit tumor growth and mitigate the risk of pneumonitis." (PMID 39772073, 2024). "This radiotherapy fraction, combined with TKIs, showed promising results in a tumor-bearing mouse model with an EGFR mutation, although there is a risk of radiation-associated pneumonitis." (PMID 39772073, 2024). "The WJOG9717L study, which compared osimertinib monotherapy with osimertinib plus bevacizumab in previously untreated Japanese patients harboring EGFR mutations, revealed that 18.3% of the patients experienced pneumonitis." (PMID 38046380, 2023). "Pneumonitis is also one of the most common SAE associated with epidermal growth factor receptor‐TKIs, with a documented incidence of 1.6%–4.3% in Japanese populations and 0.3%–1.0% in non‐Japanese populations." (PMID 37017467, 2023). "Identifying risk factors for the development of pneumonitis has been an ongoing process since the widespread use of immunotherapy began with factors such as recent radiation, use of EGFR TKIs, and combination durvalumab plus radiation clouding the picture." (PMID 37941544, 2023). "Generally, pneumonitis is a well-known adverse event associated with EGFR-TKIs, and the incidence of TKI-associated pneumonitis is higher in the Japanese population than in Western populations." (PMID 34848786, 2021). "Relapsing grade 2 pneumonitis was recorded in 1 EGFR-mutated patient receiving subsequent afatinib therapy, and the pneumonitis recovered by temporarily interrupting the afatinib and steroid therapy." (PMID 34696229, 2021). "Based on a retrospective analysis in Japanese patients, the EGFR-TKI treatment-related risk of pneumonitis and mortality are 3.5% and 1.6%, respectively." (PMID 31426531, 2019). "According to a worldwide meta-analysis, the risk for pneumonitis is at 1.7% and the mortality risk is at 0.5% following EGFR-TKI treatment." (PMID 31426531, 2019). "A prospective cohort study of drug-induced pneumonitis after erlotinib administration in patients with EGFR mutation-positive NSCLC identified pre-existing IP and low residual normal lung function (50% or less) as risk factors for developing drug-induced pneumonitis." (PMID 38611005, 2024). "However, data to fully report the efficacy and incidence of drug-induced pneumonitis for molecular-targeted therapies targeting driver gene mutations other than EGFR in NSCLC patients with comorbid IP remain insufficient." (PMID 38611005, 2024). "As ADCs have an increased risk for ILD toxicity, there may be a risk for pneumonitis if patients were to go back to an EGFR TKI afterward." (PMID 38107063, 2023). "Two EGFR-mutated patients in our study experienced grade 3 durvalumab-induced pneumonitis." (PMID 34696229, 2021). "Two of the three patients who experienced grade 3 pneumonitis were EGFR-mutated." (PMID 34696229, 2021).